PGK1 (phosphoglycerate kinase 1)
Diseases named in the same sentence as PGK1 in open-access papers (continued):
Sharing a sentence is not in itself a finding about the gene and the disease.
endometrial cancer (9 papers, 2018 to 2025). Primary or metastatic malignant neoplasm involving the endometrium (mucous membrane that lines the endometrial cavity). "It is also recently reported that in endometrial cancer, PGK-1 expression is elevated and is statistically linked to a variety of pathological indicators." (PMID 30925862, 2019). "We first showed that PGK1 expression is elevated in tumor tissues of endometrial cancer, and high PGK1 levels are associated with clinical stages and metastasis." (PMID 30925862, 2019). "Similar to a report on gallbladder cancer, we further demonstrated that high PGK1 expression was associated with poor prognosis in endometrial carcinoma patients." (PMID 29416645, 2018). "It remains to be investigated whether PGK1 could regulate chemoresistance of endometrial cancer by affecting cellular metabolism, and this possible underlying mechanism should be further investigated in future work." (PMID 30925862, 2019). "However, the specific roles and underlying mechanism of PGK1 in endometrial cancer remain largely unknown, and further exploration is required." (PMID 30925862, 2019). "Moreover, PGK-1 has been demonstrated to be overexpressed in endometrial carcinoma and to be associated with poor prognosis, while its specific function in endometrial cancer is unknown." (PMID 30925862, 2019). "In brief, the present study showed that PGK1 knockdown increased the sensitivity of endometrial cancer cells to cisplatin by down-regulating the expression of DNA repair and methylation-related genes in a HSP90-dependent manner." (PMID 30925862, 2019). "We further defined the role of PGK1 in endometrial cancer by assessing the impact of its knockdown on DNA repair and methylation." (PMID 30925862, 2019). "To further verify the effects of PGK1 on tumor growth in vivo, we constructed a nude mouse model of endometrial cancer via injection of Ishikawa cells, and found that knockdown of PGK1 expression drastically slowed tumor growth and reduced tumor size." (PMID 30925862, 2019). "Collectively, these data show that JAG2, AURKA, PGK1, and HRPT1 have the potential to be used independently as diagnostic, prognostic, or treatment biomarkers in endometrial cancer." (PMID 30679932, 2019). "We next tested the effects of PGK1 on tumor cell viability in two endometrial cancer cell lines (Ishikawa and HEC1A)." (PMID 30925862, 2019). "Knockdown of PGK1 inhibits proliferation of endometrial cancer cells, and enhances the inhibitory effect of cisplatin on cell viability." (PMID 30925862, 2019). "We have determined that there is a significant elevation of JAG2, HPRT1, AURKA, and PGK1 expression in endometrial cancer." (PMID 30679932, 2019). "In the present study, we aim to reveal the mechanism by which PGK1 regulates chemoresistance in endometrial carcinoma." (PMID 30925862, 2019). "qPCR was performed to detect expression of PGK1 in clinical tissue samples of endometrial carcinoma." (PMID 30925862, 2019). "We measured PGK1 protein-expression levels and localization in 130 endometrial carcinoma samples and 30 normal endometrial tissues by immunohistochemical staining." (PMID 29416645, 2018). "We used 30 normal endometrial tissue samples and 130 endometrial carcinoma samples, and separately evaluated PGK1 and GRP78 protein expression by immunohistochemistry." (PMID 29416645, 2018). "To investigate the prognostic value of PGK1 and GRP78 expression for endometrial carcinoma, we assessed the association between PGK1 and GRP78 expression levels and patient survival using Kaplan–Meier analysis with the log-rank test." (PMID 29416645, 2018). "In 130 endometrial carcinoma cases with prognosis information, the levels of PGK1 and GRP78 expression significantly correlated with overall survival." (PMID 29416645, 2018). "We found that PGK1 expression in endometrial carcinoma tissues was higher than that in normal endometrium tissues, consistent with earlier studies." (PMID 29416645, 2018).
endometrial cancer (continued). "The aim of this study was to measure the expression patterns of PGK1 and GRP78 in normal endometrial tissues and endometrial carcinoma, and associations between their combined effects and the pathological features of endometrial carcinoma." (PMID 29416645, 2018). "Spearman’s test demonstrated that PGK1 expression was positively correlated with GRP78 expression in the endometrial carcinoma patients (P < 0.001)." (PMID 29416645, 2018). "Specific shRNAs were employed to knockdown PGK1 expression in endometrial cancer cell lines." (PMID 30925862, 2019). "We next investigate whether the promotive effects of PGK1 on the chemoresistance in endometrial cancer cell lines is dependent on HSP90 and the downstream ERK pathway." (PMID 30925862, 2019). "At the same time, we would like to point out that PGK1 may also affect endometrial cancer chemoresistance in HSP90-independent manners, including by regulating autophagy, glycolysis, or the tricarboxylic acid (TCA) cycle." (PMID 30925862, 2019). "They proposed that the jagged canonical Notch ligand 2 (JAG2), Aurora kinase A (AURKA), phosphoglycerate kinase 1 (PGK1), and hypoxanthine phosphoribosyltransferase 1 (HRPT1) could be used independently as diagnostic, prognostic, or treatment biomarkers in endometrial cancer." (PMID 34322276, 2019). "Therefore, we propose that up-regulation of DNMTs expression may be involved in PGK1-mediated chemoresistance in endometrial carcinoma." (PMID 30925862, 2019). "In addition, the PGK1 protein was highly expressed in 44.6% (58/130) of endometrial carcinoma samples, compared with only 10.0% (3/30) of normal samples, which was significantly lower than that in the endometrial carcinoma samples (P < 0.001)." (PMID 29416645, 2018). "The results provided essential information on the functions of PGK1 and HSP90 and establish them as potential targets for endometrial cancer chemotherapy." (PMID 30925862, 2019). "Herein, we demonstrated that knockdown of PGK1 inhibited the expression of c-JUN, FOSL1, and POLD1, indicating that PGK1 regulates chemoresistance in endometrial carcinoma through upregulation of DNA repair-related proteins." (PMID 30925862, 2019). "Taken together, we elucidated in this work a regulatory axis consisting of PGK1, HSP90, ERK pathway, DNA methylation and DNA repair-related proteins to regulate cisplatin chemoresistance in endometrial carcinoma." (PMID 30925862, 2019). "Our results suggested that the co-occurrence of PGK1 and GRP78 expression is potentially an unfavorable factor for endometrial carcinoma progression." (PMID 29416645, 2018). "Owing to the limited sample size of patients in our study, further investigations are needed to confirm these findings and establish the role of PGK1 and GRP78 as a reliable clinical predictor for endometrial carcinoma outcomes." (PMID 29416645, 2018). "In this study, we systematically examined the expression levels of PGK1 and GRP78 in normal endometrium and endometrial carcinoma tissues, and analyzed the correlations between the expression of these markers and clinicopathological parameters." (PMID 29416645, 2018). "Combined PGK1 and GRP78 can improve the assessment with the prognosis of endometrial carcinoma patients." (PMID 29416645, 2018). "Immunohistochemical analysis revealed increased PGK1 and GRP78 expression in the cytoplasm of endometrial carcinoma cells compared with that in normal endometrial tissues." (PMID 29416645, 2018). "PSMC4, PUM1 and IPO8 were identified as the best reference genes combination for type 1 endometrial cancer (grades 1, 2 and 3), whereas for type 2 endometrial cancer (serous and carcinosarcoma), UBC, MRPL19, PGK1 and PPIA were the best reference genes combination." (PMID 32439920, 2020). "The results provide new insights on functions of PGK1 and HSP90, which might make them as promising targets for endometrial cancer chemotherapy." (PMID 30925862, 2019).
endometrial cancer (continued). "PGK1 has been shown to be upregulated in several cancer types, but has not been evaluated for upregulation in endometrial cancer." (PMID 30679932, 2019). "In present work, we for the first time verified that PGK1 directly binds HSP90 and that overexpression of PGK1 down-regulates cellular ATP level in endometrial cancer cell lines, which is consistent with previous finding that HSP90 ATPase is activated by terazosin through PGK1 under cellular stress." (PMID 30925862, 2019). "In the present study, we revealed the roles of PGK1 and HSP90 in endometrial carcinoma." (PMID 30925862, 2019). "In summary, we have shown for the first time that high expression of PGK1 and GRP78 might be involved in the clinical progression and poor prognosis of endometrial carcinoma." (PMID 29416645, 2018). "However, if overexpression of PGK1 was supplemented with HSP90 ATPase inhibitor 17-AAG or ERK pathway inhibitor PD98059, the sensitivity of the endometrial cancer cell lines to cisplatin was restored." (PMID 30925862, 2019). "Furthermore, our results suggest that high expression of PGK1 and GRP78 might serve as a new clinically significant biomarker for endometrial carcinoma prognosis." (PMID 29416645, 2018). "Furthermore, ROC analysis showed that combined ROC analysis of PGK1 and GRP78 could better determine the prognosis of endometrial carcinoma patients." (PMID 29416645, 2018). "However, no reports have described the role of PGK1 in endometrial carcinoma." (PMID 29416645, 2018).
gallbladder cancer (9 papers, 2017 to 2024). "Mechanically, we identified that the oncogenic function of GBCDRlnc1 in gallbladder cancer is associated with the interaction of this lncRNA and PGK1." (PMID 30953511, 2019). "However, the interaction of the long non-coding RNA (lncRNA) gallbladder cancer drug resistance-associated lncRNA1 with phosphoglycerate kinase 1 in gallbladder cancer cells prevents ATG5 degradation and induces the ATG5-ATG12 complex formation, promoting autophagy and doxorubicin resistance." (PMID 39850800, 2024). "The lncRNA GBCDRlnc1 interacts with phosphoglycerate kinase 1 (PGK1) and inhibits its ubiquitination in Dox‐resistant gallbladder cancer cells, affecting autophagy and chemoresistance of gallbladder cancer cells." (PMID 37042179, 2023). "In human gallbladder cancer tissues, lncRNA GBCDRlnc1 increases the expression of phosphoglycerate kinase 1 (PGK1), which upregulates ATG5 and ATG12 expression." (PMID 35159248, 2022). "LncRNA GBCDRlnc1 directly interacts with phosphoglycerate kinase 1 (PGK1) and increasing its protein level by inhibiting PGK1 ubiquitination in gallbladder cancer cells." (PMID 33219221, 2020). "To upregulate the expression of PGK1, we transfected gallbladder cancer cells with plasmids containing pcDNA3.1-PGK1 and validated the efficiency of overexpression by western blot." (PMID 30953511, 2019). "In this study, we found that PGK1 abrogates GBCDRlnc1-mediated autophagy and chemoresistance in drug-resistant gallbladder cancer cells, hinting that GBCDRlnc1 functions in a PGK1-dependent manner." (PMID 30953511, 2019). "(E) The protein levels of PGK1 in the parental gallbladder cancer cells under different transfection were determined by western blot assay." (PMID 30953511, 2019). "(D) The protein levels of PGK1 in Dox-resistant gallbladder cancer cells under different transfection were determined by western blot assay." (PMID 30953511, 2019). "Mechanically, we identified that GBCDRlnc1 interacts with phosphoglycerate kinase 1 and inhibits its ubiquitination in Dox-resistant gallbladder cancer cells, which leads to the down-regulation of autophagy initiator ATG5-ATG12 conjugate." (PMID 30953511, 2019). "In summary, we identified that lncRNA GBCDRlnc1 induces autophagy and drug-resistance of gallbladder cancer cells by interacting with PGK1 and preventing its degradation, which eventually upregulates ATG5-ATG12 expression." (PMID 30953511, 2019). "The rescue experiments indicated that PGK1 overexpression abrogated the inhibitory effect of GBCDRlnc1 knockdown on the chemoresistance and autophagy of gallbladder cancer cells." (PMID 30953511, 2019). "To explore the effects of GBCDRlnc1 on PGK1, we manipulated the expression levels of GBCDRlnc1 in gallbladder cancer cells and detected the alteration of PGK1 mRNA and protein levels." (PMID 30953511, 2019). "(D) Relative expression of PGK1 in Dox-resistant gallbladder cancer cells under different transfection was determined by qRT-PCR." (PMID 30953511, 2019). "To further evaluate the positive correlation between GBCDRlnc1 and PGK1, we performed immunohistochemical staining to examined the expression level of PGK1 in the divided high- and low-GBCDRlnc1 human gallbladder cancer tissues." (PMID 30953511, 2019). "To silence the expression of PGK1 in drug-resistant gallbladder cancer cells, we designed two PGK1-specific siRNAs and chose the si-PGK1–2 for PGK1 knockdown." (PMID 30953511, 2019). "(A) The protein levels of PGK1 in Dox-resistant gallbladder cancer cells under different transfection were determined by western blot assay." (PMID 30953511, 2019). "Given these, these results suggested that the direct interaction between GBCDRlnc1 and PGK1 prevents the ubiquitination and degradation of PGK1 in gallbladder cancer cells in vitro." (PMID 30953511, 2019).
gallbladder cancer (continued). "Furthermore, we confirmed that PGK1 knockdown represses the autophagic flux of drug-resistant gallbladder cancer cells at initial stage, which is in accord with the effect of GBCDRlnc1 knockdown on autophagy." (PMID 30953511, 2019). "To explore whether PGK1 is involved in gallbladder cancer cells chemoresistance, we performed western blot to examine the expression levels of PGK1 in Dox-resistant gallbladder cancer cells and their parental cells." (PMID 30953511, 2019). "Given this, we supposed that GBCDRlnc1 might act as a “molecular decoy” in gallbladder cancer cells, which directly binds to PGK1 and interferes the interaction of PGK1 and ubiquitin." (PMID 30953511, 2019). "Thus, we concluded that the function of GBCDRlnc1 on the chemoresistance and autophagic activity of gallbladder cancer cells is through its positive mediation of PGK1 in vitro." (PMID 30953511, 2019). "Moreover, the results of western blot and stubRFP-sensGFP-LC3 staining indicated that PGK1 knockdown could repress the autophagic flux of drug-resistant gallbladder cancer cells at initial stage." (PMID 30953511, 2019). "Therefore, GBCDRlnc1/PGK1/ATG5-ATG12 conjugate signaling pathway might be a novel therapeutic target for gallbladder cancer chemotherapy." (PMID 30953511, 2019). "The mRNA levels of PGK1 were not significantly changed when GBCDRlnc1 was silenced or overexpressed in gallbladder cancer cells." (PMID 30953511, 2019).
renal clear cell carcinoma (8 papers, 2020 to 2025). "For example, phosphoglycerate kinase 1 (PGK1) plays a role in the development of renal clear cell carcinoma and resistance to sorafenib by activating the C-X-C motif chemokine receptor 4 (CXCR4)/ERK pathway, thereby accelerating glycolysis." (PMID 40837407, 2025). "Research has indicated that PGK1 enhances glycolysis via CXCR4/ERK pathway activation, which is associated with sorafenib resistance in clear cell renal cell carcinoma." (PMID 40786054, 2025). "In clear cell renal carcinoma cells (ccRCC), Myc is recruited to the promoter region of PGK1, showing that Myc directly interacts with PGK1." (PMID 37723547, 2023). "Generally, PGK1 upregulation contributes to tumorigenesis and sorafenib resistance of renal clear cell carcinoma via activating CXCR4/ERK signaling pathway and accelerating glycolysis." (PMID 35121728, 2022).
bladder cancer (7 papers, 2015 to 2024). "The overexpression of PGK1 has reportedly been associated with cisplatin resistance in ovarian and bladder cancer cells, which might be because PGK1 can induce multi-drug resistance through an MDR-1 independent pathway." (PMID 36292976, 2022). "We found that GARS promote the bladder cancer progression in human urinary bladder carcinoma cell lines, T24 and 5637, through enhancing pentose phosphate pathway flux by inhibiting activities of PGK1 and PKM2." (PMID 35659036, 2022). "Recently, HIF-1α activation and subsequent PGK1 up-regulation has also been demonstrated in bladder cancer." (PMID 26468005, 2015). "This study sought to investigate the specific role of PGK1 in bladder cancer (BLCA)." (PMID 39315723, 2024). "Finally, we found that GARS promotes the bladder cancer progression in human urinary bladder carcinoma cell lines, T24 and 5637, through enhancing pentose phosphate pathway flux by inhibiting activities of PGK1 and PKM2." (PMID 35659036, 2022). "JMJD1A promotes the transcription of PGK1 by regulating H3K9me2 levels in the PGK1 promoter region and interacting with HIF-1α to regulate the glucose metabolism pathway in bladder cancer cells, thus regulating the progression of bladder carcinoma." (PMID 37394582, 2023).
benign prostatic hyperplasia (6 papers, 2021 to 2025). A non-cancerous nodular enlargement of the prostate gland. "Previous studies showed that terazosin (TZ), an FDA-approved drug developed to treat hypertension and benign prostatic hyperplasia, has an additional target, phosphoglycerate kinase 1 (PGK1), the first ATP-generating enzyme in glycolysis." (PMID 38377207, 2024). "PGK1 activity can be increased using an off-target effect of the FDA-approved small molecule terazosin, which is normally prescribed for benign prostatic hyperplasia or hypertension." (PMID 35963713, 2022).
lymph node metastasis (6 papers, 2018 to 2025). "Previous results have indicated an association between PGK1 expression and tumor invasion and lymph node metastasis." (PMID 39315723, 2024). "Here, significant associations between high PGK1 expression and FIGO stage, histological grade, pathological type, and lymph node metastasis were identified." (PMID 29416645, 2018). "The low expression of the proteins LTA4H, PGK1, NDRG1, COL6A1, and ITGAV in the saliva samples was associated with lymph node metastasis and advanced clinical staging (crosstabulation and chi-square test, P value < 0.05)." (PMID 30185791, 2018). "Furthermore, compared with the endometrial tumor tissues without lymph node metastasis (n = 42), elevated expression of PGK1 was observed in endometrial tumor tissues with lymph node metastasis (n = 14)." (PMID 30925862, 2019). "Additionally, high PGK1 expression is significantly associated with poor prognostic features, including low differentiation, advanced TNM staging, lymph node metastasis, and tumor diameter ≥1.0 cm, reinforcing the critical role of PGK1 in the progression of thyroid papillary carcinoma." (PMID 40771921, 2025). "Interestingly, SRM-MS analysis showed CSTB, LTA4H, PGK1, COL6A1, ITGAV, and NDRG1 were significantly downregulated in patients with lymph node metastasis." (PMID 30185791, 2018). "However, the PGK1 expression level did not significantly correlate with FIGO stage, lymph node metastasis, or pathologic type (P > 0.05)." (PMID 34277429, 2021).
Parkinsonism (6 papers, 2017 to 2025). Characteristic neurologic anomaly resulting from degeneration of dopamine-generating cells in the substantia nigra, a region of the midbrain, characterized clinically by shaking, rigidity, slowness of movement and difficulty with walking and gait. "This discovery was followed by a paper detailing patients of juvenile-onset, levodopa-responsive parkinsonism with evidence of nigrostriatal dysfunction attributed to PGK1 deficiency, cementing glycolysis’ involvement in PD." (PMID 40681352, 2025).